GTPBP4 (GTP binding protein 4)
Diseases named in the same sentence as GTPBP4 in open-access papers (continued):
Sharing a sentence is not in itself a finding about the gene and the disease.
hearing loss (1 paper, 2022). "A de novo heterozygous variant of GTPBP4 was identified as the candidate cause of the sporadic hearing loss in family 1696." (PMID 35248088, 2022). "The other five genes (SVEP1, CACNG1, GTPBP4, PCNX2, and TBC1D8) were categorized as Tier 4 genes, with no known association with hearing loss." (PMID 35248088, 2022).
Hypertension (1 paper, 2020). The presence of chronic increased pressure in the systemic arterial system. "On the basis of this information, it can be assumed that a nonsynonymous substitution presumably affecting the structure and/or function of GTPBP4 may be associated with hypertension in both OXYS and ISIAH rats." (PMID 32429546, 2020).
lung carcinoma (1 paper, 2022). "So far, investigations on GTPBP4 in lung cancer, particularly non-small cell lung cancer (NSCLC), have been published very seldom." (PMID 36405249, 2022). "From this study, new research ideas emerge to explore GTPBP4 as a biomarker and therapeutic target for early diagnosis and treatment of lung cancer." (PMID 36405249, 2022). "In order to further verify the results of in vitro experiments, we used tail vein injection of LLC-WT and LLC-GTPBP4 KO cells to establish a mouse lung cancer model in C57BL/6 mice and observed the effect of GTPBP4 protein on the development of NSCLC." (PMID 36405249, 2022). "To examine the expression of GTPBP4 in lung cancer, we assessed the published data for cancer and normal tissues from the TCGA databases." (PMID 36405249, 2022). "In addition, we developed a mouse lung cancer model in order to better investigate the significance of GTPBP4." (PMID 36405249, 2022). "To investigate whether the expression level of GTPBP4 is connected to the EMT state of lung cancer cells, we conducted a preliminary investigation in which we looked at the expression level of GTPBP4." (PMID 36405249, 2022). "GTPBP4 also had a good value in the diagnosis of lung cancer; the area under the receiver operating characteristic curve (AUC) was 0.882, indicating that GTPBP4 might be a good biomarker for the diagnosis of lung cancer." (PMID 36405249, 2022). "It has also been reported that silencing GTPBP4 in lung cancer cell lines results in significant inhibition of cell proliferation, angiogenesis, clone formation, and tumor development in nude mice although the specific processes and signaling pathways involved in NSCLC remain unclear." (PMID 36405249, 2022). "We further detected and analyzed the expression of GTPBP4 protein in human NSCLC cell lines H838, H2347, Calu-1, and A549 and mouse lung cancer cells LLC by immunoblotting." (PMID 36405249, 2022). "To investigate whether GTPBP4 promoted NSCLC proliferation by regulating EMT, we examined the effect of knockdown of GTPBP4 on EMT-related proteins in NSCLC cell line A549, Calu-1, and mouse lung cancer tissues." (PMID 36405249, 2022).
lymph node metastasis (1 paper, 2021). "However, in patients grouped only by the distance to lymph node metastasis, GTPBP4 increased with the degree of lymph node metastasis, and the expression level increased (P < 0.05)." (PMID 34712323, 2021).
non-small cell lung carcinoma (1 paper, 2022). A group of at least three distinct histological types of lung cancer, including non-small cell squamous cell carcinoma, adenocarcinoma, and large cell carcinoma. "The expression and regulation of GTPBP4 in non-small cell lung cancer (NSCLC) are not well understood." (PMID 36405249, 2022).
cancer (10 papers, 2014 to 2024). A tumor composed of atypical neoplastic, often pleomorphic cells that invade other tissues. "Till now, the function and detailed underlying mechanism of GTPBP4 in malignant tumors have been poorly uncovered." (PMID 29212203, 2017). "The expression of GTPBP4 increased with the increase of cancer metastasis in lymph nodes (P < 0.01)." (PMID 34712323, 2021). "Although GTPBP4 has been most often found to act as an oncogene, it has also been described as a suppressor gene in rare cases, such as in neurofibromatosis 2 (NF2), suggesting that the role of GTPBP4 depends on the specific type of cancer." (PMID 33134380, 2020). "GTPBP4 expression was increased in most human cancer types when compared with adjacent normal tissues, and this difference was significant in LUAD primary tumor tissues." (PMID 33134380, 2020). "Previous studies had shown that GTPBP4 can induce cell proliferation and enhance cell colony formation in some cancer types." (PMID 33134380, 2020). "Till now, a small number of existing studies have found a contradictory dual role of GTPBP4 in cancer." (PMID 29212203, 2017). "DDX24, GTPBP4, and BOP1, for example, are involved in RNA metabolism, cell-cycle regulation, and ribosome biogenesis, respectively, reflecting their substantial influence on cellular processes linked to cancer progression." (PMID 39001461, 2024). "The results showed that GTPBP4 had an upregulated expression in most cancer types." (PMID 34712323, 2021). "Subsequently, we observed the expression of GTPBP4 in different cancer types." (PMID 34712323, 2021). "However, recent studies have indicated that the role of GTPBP4 in malignant tumor types is double sided." (PMID 33134380, 2020). "A small number of existing studies have found a contradictory dual role of GTPBP4 in cancer." (PMID 29212203, 2017). "There is limited literature regarding the functional role of GTPBP4 in the context of cancer." (PMID 24944582, 2014). "It suggests that GTPBP4 may affect cancer cells by affecting the biosynthesis of ribosomes." (PMID 34712323, 2021). "Therefore, we speculated that the regulation of ribosome biogenesis by GTPBP4 plays an essential role in various types of cancer." (PMID 33134380, 2020). "However, the different expression levels of GTPBP4 (downregulated or upregulated) were found in those malignant tumors, suggesting that GTPBP4 may act as an oncogene or a suppressor gene mainly dependent upon the specific cancer type." (PMID 29212203, 2017). "The results showed a significant upregulation of GTPBP4 in several human cancer subtypes (P < 0.05), including LUAD compared with noncancerous lung tissues in TCGA." (PMID 36405249, 2022).
tumor (8 papers, 2017 to 2025). "GTPBP4 is a GTPase that plays a crucial role in 60S ribosome biogenesis and is responsible for tumor metastasis in CRC by disrupting the actin cytoskeleton, which is mediated by the reduced RhoA activity." (PMID 39949372, 2025). "The relationship between GTPBP4 and tumor pathogenesis is currently under investigation, and various study results suggest that GTPBP4 plays different roles in different diseases." (PMID 36405249, 2022). "The study of the immune microenvironment provides a foundation for understanding GTPBP4’s role in the tumor microenvironment." (PMID 35784753, 2022). "The results showed that the tumor volume in the GTPBP4 overexpression group was significantly increased, while the tumor volume in the GTPBP4 inhibited expression group was significantly reduced." (PMID 34712323, 2021). "Through nude mouse tumorigenicity assay, the effect of GTPBP4 expression on tumor growth in vivo was explored." (PMID 34712323, 2021). "At the same time, the tumor weight in the GTPBP4 overexpression group also increased significantly and decreased in the GTPBP4 inhibited expression group." (PMID 34712323, 2021). "In the present study, we have demonstrated that the expression of GTPBP4 is higher in tumor tissues than in adjacent normal control." (PMID 33134380, 2020). "The tumor size was significantly smaller in nude mice injected with cells infected with lentiviruses expressing GTPBP4-shRNA than that in the control group." (PMID 29212203, 2017). "Further studies showed that GTPBP4 acted as a tumor suppressor gene by regulating Merlin and cyclin D1 to inhibit cell proliferation." (PMID 29212203, 2017). "GTPBP4 expression was higher in LUAD primary tumor tissues than in adjacent normal tissues." (PMID 36405249, 2022). "The tumor volume was smaller in nude mice injected with GTPBP4-shRNA cells at all 7 time points, and the tumor weight was also substantially lower in nude mice injected with GTPBP4-shRNA cells than that in the control group." (PMID 29212203, 2017). "The immunohistochemistry (IHC) results demonstrated that DYNC1H1, GTPBP4, PRKDC, RBM19, SF3B4, SPATS2 and TAF9 were significantly increased in HCC tumor cells compared to normal hepatocytes." (PMID 33411682, 2020). "Based on the anti-tumor activity of TP and its toxicity to LUAD cells, our study indicated that RNA interference of GTPBP4 in A549 and H1299 cells significantly increased sensibility to TP." (PMID 33134380, 2020). "SMMC-7721 cells infected with lentiviruses expressing either control non-target shRNA or GTPBP4-shRNA were used and injected subcutaneously into nude mice, and then the tumor volume and weight were examined." (PMID 29212203, 2017).
infection (2 papers, 2024 to 2025). The state of being infected such as from the introduction of a foreign agent such as serum, vaccine, antigenic substance or organism. "Using microscopy, we confirmed the prediction of our chaperone interaction analysis, observing colocalization of DDX10, DDX18, DDX50, and GTPBP4 with VICE domains upon infection with HSV-1." (PMID 40577456, 2025). "The results showed that GTPBP4 transcription was significantly upregulated as the infection progressed." (PMID 38516932, 2024). "The WT mice infected with FMDV started to die at 3 d post-infection (dpi) and all mice died by 4 dpi, while the Gtpbp4± mice infected by FMDV started to die at 3 dpi and survived 20% at 7 dpi, indicating that GTPBP4 deficiency decelerated FMDV-induced the death of mice." (PMID 38516932, 2024). "The protein level of GTPBP4 gradually increased as infection progressed." (PMID 38516932, 2024).
GTPBP4 also shares sentences with these, for which no sentence is quoted: bladder cancer (1 paper); bladder urothelial carcinoma (1); clear cell renal cell carcinoma (1); schwannoma (1).